G6PD (glucose-6-phosphate dehydrogenase)
Diseases named in the same sentence as G6PD in open-access papers (continued):
Sharing a sentence is not in itself a finding about the gene and the disease.
malaria (continued). "G6PD catalyses the first step of the pentose phosphate pathway and enzyme variants, frequent in some populations have been selected because they confer resistance to malaria, are associated with hemolysis in the presence of oxidizing agents including several drugs." (PMID 25713697, 2014). "Thus, the observed reduced frequency of G6PD-deficiency is consistent with the hypothesis that G6PD-deficiency protects against severe malaria." (PMID 23039275, 2012). "Moreover, eryptosis is enhanced in a variety of clinical conditions including iron deficiency, sickle-cell anaemia, beta-thalassaemia, glucose-6-phosphate dehydrogenase (G6PD)-deficiency, phosphate depletion, Haemolytic Uremic Syndrome, sepsis, malaria and Wilson disease." (PMID 19442289, 2009). "For instance, 10% of males and 24% of females with the G6PD A- haplotype (i.e., women who were homozygous for G6PD A-) had normal G6PD activity in a large-scale clinical trial of malaria patients in 6 African countries." (PMID 41575919, 2026). "The use of quantitative G6PD testing prior to tafenoquine or primaquine was operationally feasible and had acceptable safety when deployed in community hospitals and malaria clinics in Thailand." (PMID 40274286, 2025). "Host genetic variations, notably sickle-cell trait (hemoglobin S-HbS) and glucose-6-phosphate dehydrogenase (G6PD) deficiency, affect malaria susceptibility and disease outcomes by altering erythrocyte physiology and inhibiting parasite growth." (PMID 40723909, 2025). "Include malaria test-and-treat tactics insisting on appropriate artemisinin-based combination therapy, in tandem with G6PD screening before primaquine/tafenoquine in Plasmodium vivax." (PMID 41473720, 2025). "In 2017, Thailand and India were the first malaria-endemic countries to approve a point-of-care quantitative G6PD test." (PMID 40274286, 2025). "Some of the genes that confer resistance to malaria are among the most variable genes in the human genome, as seen in the human leukocyte antigen (HLA), G6PD, globin, and ABO genes." (PMID 40709108, 2025). "Balancing malaria control efforts with patient safety will require expanded pre-treatment screening, alternative drug regimens, and the development of G6PD-safe antimalarial therapies." (PMID 40486677, 2025). "At present, only one commercially available quantitative product, the STANDARD G6PD test (SD Biosensor, Republic of Korea), has been widely used in the context of malaria case management." (PMID 40597115, 2025). "Glucose-6-phosphate dehydrogenase (G6PD) deficiency is the most common enzymatic disorder globally, affecting over 400 million individuals, particularly in malaria-endemic regions of Africa, Southeast Asia, and the Mediterranean." (PMID 41002317, 2025). "The results of this study led to the implementation of semi-quantitative G6PD testing and tafenoquine in the Brazilian Public Health System; this is the first malaria-endemic country to implement it." (PMID 40978565, 2025). "It will be crucial to integrate G6PD testing into malaria prevention efforts, train healthcare workers, and establish screening procedures." (PMID 40225210, 2025). "Since Brazil is committed to equitable access to treatment, all facilities that treat malaria patients must provide G6PD screening to enable tafenoquine prescription." (PMID 40978565, 2025). "Updated guidance includes G6PD screening to prevent hemolysis, active and extended post-deployment surveillance, and the awareness of delayed presentation with malaria after prophylaxis." (PMID 40639370, 2025). "Key themes included policy alignment, phased implementation of tafenoquine and G6PD testing, planning and funding constraints, private sector engagement, and the importance of sustained dialogue between researchers and malaria program leaders." (PMID 41219866, 2025).
malaria (continued). "In the daily primaquine group, one serious adverse event occurred in a G6PD intermediate patient with severe malaria and severe thrombocytopenia requiring transfusion with leucocyte-depleted pooled platelet concentrate for idiopathic thrombocytopenic purpura." (PMID 40274286, 2025). "Venous blood samples were collected into K2EDTA (for full blood count, G6PD activity and malaria microscopy) and serum‐separator tubes (SSTs) (sera for measurement of epo concentrations and anti‐epo antibodies using ELISA kits)." (PMID 41050847, 2025). "One-way sensitivity analyses showed that the results were most sensitive to severity and mortality due to vivax malaria, the lifetime and number of semiquantitative G6PD analysers needed, cost per malaria episode and per G6PD test strips, and life expectancy." (PMID 38194420, 2024). "One major limitation is their potential for causing hemolysis in patients with a deficiency in glucose-6-phosphate dehydrogenase (G6PD), a genetic condition that affects a significant proportion of populations in malaria-endemic regions." (PMID 39598540, 2024). "Reassuringly, results were similar in sensitivity analyses restricted to patients with G6PD activity measured during acute malaria." (PMID 37748497, 2024). "Despite theoretical variations in G6PD activity during haemolysis, the present study showed that in each patient, G6PD activity remained stable during a malaria episode." (PMID 38725027, 2024). "For example, in Bangladesh, a key barrier to quantitative G6PD testing adoption is the diminishing importance of malaria as perceived by both policy makers and the affected communities." (PMID 38837977, 2024). "Cambodia’s national malaria program has implemented G6PD testing using the Biosensor as part of vivax case management up to the health center level." (PMID 39028699, 2024). "Reviews of national policies on the use of PQ for radical cure and G6PD testing published in 2018 and 2023 show substantial variation across malaria endemic countries, and highlight a gap between policy and practice." (PMID 39236082, 2024). "Although, considering the low number of malaria cases in the extra-Amazon region—less than 1% of the total country cases—implementing the G6PD testing followed by tafenoquine treatment is feasible." (PMID 39420377, 2024). "The impact of radical cure on the reduction of vivax recurrences, enabled by the implementation of G6PD testing, was apparent to malaria officials, healthcare providers, and patients alike (po2, hc6, pp35)." (PMID 39028699, 2024). "Six clusters where anaemia, malaria and blood disorders (HbS, HbC or G6PD) overlapped were identified, and these included the following countries: Liberia, Sierra Leonne, Guinea, Ghana, Côte d’ivoire, Nigeria and Benin." (PMID 39696874, 2024). "For Brazil to achieve malaria elimination, successful implementation of quantitative G6PD testing and single-dose tafenoquine for P. vivax radical cure is critical." (PMID 38837977, 2024). "We present the results based on quantile levels α1 = 0.2 and α2 = 0.8, to model the relationship between a low quantile of malaria and a high quantile of G6PD." (PMID 38179076, 2024). "Another pertinent point about G6PD testing is that studies have found that repeat testing at different times can produce variable results in malaria patients." (PMID 39236082, 2024). "We explore how malaria service providers and recipients experience, perceive, and receive G6PD testing and examine the impact of introducing G6PD tests as a part of radical cure treatment for vivax malaria." (PMID 39028699, 2024). "The difficulty in comprehending the significance of G6PD enzyme activity and its importance in malaria treatment initially presented a barrier for HCP understanding." (PMID 38837977, 2024).
malaria (continued). "In this context, the fused enzyme G6PD::6PGL has been proposed as a promising specific target for the search and development of new treatments for parasitic diseases, including malaria, trichomoniasis, and giardiasis." (PMID 38257939, 2024). "Recently updated malaria guidelines in Brazil require G6PD screening before administering primaquine at health facilities that have the capacity to provide G6PD testing." (PMID 38194420, 2024). "The main challenge to implementing G6PD testing was that only 49.2% (437/888) of eligible patients reached health centers for G6PD testing following malaria diagnosis by community health workers." (PMID 39028699, 2024). "malaria with G6PD activity of 30% or higher, enrolled from 18 studies, and is the largest study to assess the risk of haemolysis with different primaquine daily doses." (PMID 37748497, 2024). "Given that the malaria burden primarily resides in hard-to-reach areas (e.g., forests), the availability of G6PD testing in those areas would be an issue given its infrastructural limitations." (PMID 38395925, 2024). "The finding of a positive correlation between low quantile of malaria and a high quantile of G6PD is odd." (PMID 38179076, 2024). "Eight vivax endemic countries have recently started implementing the STANDARD G6PD test (Biosensor), and several others are preparing to use the test as part of national malaria control treatment strategies to improve radical cure treatment." (PMID 39028699, 2024). "treatment algorithm based on G6PD status, age, and pregnancy and breastfeeding status in two malaria-endemic regions in Brazil." (PMID 38365417, 2024). "Experts were also asked about the importance of having a point of care qualitative diagnostics for G6PD available for the national malaria programs and 90% (18/20) responded positively." (PMID 38776349, 2024). "This was also identified in a previous study of quantitative G6PD testing prior to primaquine, with regular refresher training particularly needed in locations with lower malaria caseloads." (PMID 38837977, 2024). "Decentralized malaria care initiatives with CHWs have successfully reduced malaria in remote areas and are being implemented for radical treatment with G6PD testing in Cambodia." (PMID 39319292, 2024). "In many malaria-endemic settings, the use of G6PD testing before antimalarial treatment is logistically and financially challenging." (PMID 37748497, 2024). "This review is the first systematic review of the effect of G6PD status, which includes only malaria patients receiving anti-malarial agents." (PMID 36872344, 2023). "The WHO recommends G6PD activity assessment prior to administration of PQ for radical cure, but there is limited access to practicable assays in malaria-endemic regions." (PMID 37604475, 2023). "By comparing the results and annotating the variants from all groups and ethnicities, we hope to improve G6PD health care and malaria eradication for the Orang Asli population." (PMID 38085718, 2023). "Identification of remaining high-risk areas may become more important to understand G6PD distribution in other parts of the country which is very important for future malaria control and elimination and allowing resources to be targeted to areas that remain at high risk of malaria transmission." (PMID 38062464, 2023). "Increasing the number of facilities to which the test was deployed and decreases in the malaria cases resulted in higher per patient cost for incorporating G6PD testing into the system." (PMID 37242359, 2023). "There were several limitations in this study, i.e., heterogenous species of malaria parasites, various type and dose of administered drugs, small sample size in G6PD groups, and diverse method of outcomes measurement." (PMID 36872344, 2023).
malaria (continued). "In a scenario that reflects a context of malaria elimination, with 400 cases and 100 facilities, the estimated total financial cost to the health system to adopt G6PD testing is USD 32,929, or USD 82 per patient." (PMID 37242359, 2023). "These various limiting factors make the spectrophotometry assay unsuitable for routine G6PD testing in most malaria-endemic countries and resource-limited settings." (PMID 37388931, 2023). "HCPs at hospitals and malaria program managers from district hospitals reported that the most appropriate staff to run the G6PD test are laboratory technicians because they are trained properly and have experience with similar assays." (PMID 37242359, 2023). "This study aimed to elucidate the G6PD molecular heterogeneity in this subethnic group which is important for malaria elimination." (PMID 38085718, 2023). "More emphasis should be placed on screening for G6PD status and proper and safe use of Primaquine in the elimination of malaria among this indigenous population." (PMID 38085718, 2023). "For example, the belief that blood is sacred influenced patients’ aversion to testing in the context of malaria diagnosis, a phenomenon likely to impact acceptance of any G6PD PoC as well." (PMID 37242320, 2023). "Most of the household participants accepted the study activities for G6PD testing and allocating the malaria medicines; however, some interviewed noted suspicions of strangers and individuals not from their communities." (PMID 37438774, 2023). "We describe the current state of policy and implementation of routine point-of-care G6PD testing in malaria endemic countries and highlight key knowledge gaps that hinder broader implementation." (PMID 37242320, 2023). "Mutation of the glucose-6-phosphate dehydrogenase (G6PD) gene is also widely prevalent, with an estimated 8% frequency across malaria-endemic countries." (PMID 37340364, 2023). "This study investigated the operational feasibility of introducing point-of-care quantitative glucose-6-phosphate dehydrogenase (G6PD) testing into malaria case management practices." (PMID 37242359, 2023). "The male median G6PD value on the STANDARD G6PD test is statistically consistent across varied contexts and populations (aged two years and older), including in malaria-endemic settings, with the exception of newborns." (PMID 37824592, 2023). "The recommended dose of PQ in all vivax and ovale malaria with G6PD normal (G6PDn) status is 0.25–0.5 mg/kg/day for 14 days, whereas in G6PD deficiency (G6PDd) patients, 0.75 mg/kg/week for eight weeks is recommended." (PMID 36872344, 2023). "Realizing the potential of point of care G6PD tests to do so will require a clear understanding of the challenges and transitions that routine malaria case management will need to undergo to adopt them successfully." (PMID 37242359, 2023). "Occurrence of haemoglobinuria have also been described in patients with normal erythrocyte G6PD activity who were administered quinine for severe malaria." (PMID 36609299, 2023). "Despite these challenges, countries across the GMS, including Cambodia, are actively working to scale up implementation of G6PD testing and primaquine use to address P. vivax reservoirs and accelerate progress toward malaria elimination." (PMID 37353790, 2023). "In a scenario with a moderate malaria burden of 3200 cases and 500 health facilities offering G6PD testing, the estimated total financial cost to the health system to adopt G6PD testing is USD 164,741, or USD 51 per patient." (PMID 37242359, 2023). "Our findings highlight the importance of determining G6PD status in all Malaysian Orang Asli populations, for a greater emphasis on the proper and safe use of Primaquine for malaria elimination." (PMID 38085718, 2023). "In the context of the end stages of malaria elimination, it is unlikely that G6PD screening will be cost-effective in the short-term." (PMID 37242320, 2023).
malaria (continued). "G6PD levels should be ascertained in all patients withPv malaria, and daily PQ prophylaxis should be given to those patients with normal G6PD levels." (PMID 35464047, 2022). "We enrolled 335 patients with malaria in Bangladesh, Indonesia, and Ethiopia and measured G6PD activity in all participants." (PMID 35544453, 2022). "With the availability of donor funding for quantitative STANDARDTM G6PD tests, the national malaria program in Laos is considering scaling up the rollout of these tests up to the health center level in addition to the hospital level." (PMID 35468145, 2022). "There is significant selective pressure on the G6PD gene in malaria-endemic areas resulting G6PDd prevalence is exceptionally high in some areas of Africa, the Middle East, and South Asia." (PMID 36339224, 2022). "Identification of distribution pattern of G6PD and malaria incidence can provide valuable insights for deliberating the relatedness." (PMID 36339224, 2022). "At the time of this study, the Cambodian national malaria guidelines recommended radical cure with primaquine but only if preceded by a G6PD test." (PMID 36264996, 2022). "When malaria cases become very low and the funding landscape shrinks, having G6PD tests only at the hospital level likely becomes the most natural choice from a cost-effectiveness perspective." (PMID 35468145, 2022). "In this longitudinal study we have quantified the change in G6PD activity before and after an acute episode of malaria in the same individuals." (PMID 35544453, 2022). "All participants were followed up and a second G6PD measurement was collected between 6 and 33 months after enrolment if participants were free of malaria." (PMID 35544453, 2022). "The need for G6PD testing was previously echoed by malaria programmes to administer a shorter primaquine regimen and address low adherence to anti-malarials in Laos PDR, Cambodia and Thailand." (PMID 34983549, 2022). "The deficiency of the enzyme glucose-6-phosphate dehydrogenase (G6PD), which follows a geographic prevalence pattern that has been related to malaria selection, is associated with hemolytic anemia." (PMID 36191877, 2022). "All three participants with normal G6PD activities during malaria and intermediate activities during follow up, had borderline G6PD activity (60% to 70%) at the first measurement and the mean increase in G6PD activity during follow up was less than 20%." (PMID 35544453, 2022). "In our present study, we characterised the polymorphisms of G6PD and HBB genes in the Senegalese population, two-loci previously associated with protection against severe malaria." (PMID 35811813, 2022). "When comparing the same individual’s G6PD activity during malaria and again during follow up, enzyme activity was -10.4% (95% confidence interval [95%CI]: -13.9 to -6.9) lower during follow up." (PMID 35544453, 2022). "Conversely of the 290 individuals categorized as G6PD normal during follow up, 3 (1.0%) participants were classified as G6PD intermediate during the malaria episode." (PMID 35544453, 2022). "Administration of G6PD testing and malaria diagnosis using real-time PCR were recommended to better understand the burden of vivax malaria and develop malaria elimination approaches." (PMID 34983549, 2022). "In Ethiopia only one individual had reduced G6PD activity during follow up, a 25-year-old male with 61% enzyme activity during malaria and 62% during follow up." (PMID 35544453, 2022). "In the longitudinal monitoring of G6PD activity before (Day 0) and after (Day 28) treatment, there was a total of 174 malaria patients with complete haematological data were analysed." (PMID 36038921, 2022). "Malaria patients with <30% of normal G6PD activity can receive primaquine with a dose adjustment (45 mg weekly dose for 8 weeks) under medical supervision, and tafenoquine is only prescribed to those with more than 70% G6PD activity." (PMID 36508454, 2022).